TGFB1 (transforming growth factor beta 1)
Diseases named in the same sentence as TGFB1 in open-access papers (continued):
Sharing a sentence is not in itself a finding about the gene and the disease.
breast cancer (continued). "TGFβ1 has also been the object of intense investigation due to its pathological relevance for breast cancer where it acts as a tumor suppressor in premalignant lesions and at later stages promotes metastasis through induction of epithelial-to-mesenchymal transition (EMT)." (PMID 24262428, 2013). "In summary, the present study on TGFB1 T29C and TGFBR1 6A/9A polymorphisms in relation to breast cancer risk has revealed important differences between the genotypes and allele frequencies in premenopausal Maharashtrian women, compared to Parsi and White women." (PMID 21829601, 2011). "To date, the only SNP associated with breast cancer risk with genome-wide statistical significance (P < 10-7) coming from candidate gene approaches is CASP8; more equivocal evidence has been reported for SNPs in TGFB1 and ESR1, among others." (PMID 21194473, 2010). "Finally, TGFβ1 is a ligand that regulates a signaling pathway that becomes deregulated in many types of malignancies including breast cancer." (PMID 20576088, 2010). "Polymorphisms in the promoter region of TGFB1 are not likely to be associated with large increases in breast cancer risk overall among Caucasian women." (PMID 17848193, 2007). "In conclusion, polymorphisms in the promoter region of TGFB1 are not likely to be associated with large increases in breast cancer risk overall among Caucasian women." (PMID 17848193, 2007). "Nevertheless, whereas the elevated expression of TGFβ1 is described to associate with disease progression in a number of studies, others studies failed to reveal diagnostic or predictive value of TGFβ1 for breast cancer patients." (PMID 16404434, 2006). "Furthermore, a few number of studies demonstrated that TGFβ1 was related to favorable outcome for patients with breast cancers." (PMID 16404434, 2006). "Interestingly, we found that TGFβ1 mRNA was highly encapsulated in the RNA droplets, which lowered the immunosuppressive capability of the tumor cells and triggered marked antitumor reactions in a mouse breast cancer model." (PMID 36209170, 2022). "Activation of TGFβ1 or interleukin-8 (IL-8) and interleukin-6 (IL-6) secretion could be activated upon stromal injuries induced in the bone marrow and therefore reactivate dormant breast cancer cells." (PMID 36430404, 2022). "However, as TGFB1 is known as both a suppressor and promoter of breast cancer, the precise mechanisms to which it contributes to cancer risk remain unclear." (PMID 33761981, 2021). "However, a better understanding of the precise cell types and signalling pathways that result in the tumour-promoting effects of TGFB1 could lead to new approaches for breast cancer prevention in the future." (PMID 33761981, 2021). "Moreover, TGFβ1 was found to upregulate miR-181a and downregulate miR-96 in breast cancer cells." (PMID 32512882, 2020). "However, while IGF-1 abundance is reported to correlate with both, breast cancer cell proliferation and metastatic potential, TGFβ1 is thought to promote primarily ECM and niche formation, cytoskeletal reorganization, cell motility, and invasion, but not cell proliferation." (PMID 30805306, 2019). "Moreover, whereas treatment with TGFβ1 had little impact on ID2 expression in either mouse mammary carcinoma or human breast cancer cells, BMP7 treatment resulted in a > 50-fold increase in ID2 mRNA levels and this level of expression was sustained for at least 5 days following BMP7 withdrawal." (PMID 30642388, 2019). "As a result, TGFB1 might play roles in connecting obesity and breast cancer." (PMID 29156709, 2017). "We delineate here a novel role of lysosomal cysteine cathepsin activity during TGFβ-1 induced EMT of mammary cancer cells which were established by continuous propagation of primary cancer cells derived trom the MMTV-PyMT mouse model for metastasizing breast cancers." (PMID 25744631, 2015).
breast cancer (continued). "Thus, the effects of higher frequency of TGFB1*29C allele, alone and in association with the lower frequency of TGFBR1*6A allele, may have implications for the lower incidence of breast cancer in this population." (PMID 21829601, 2011). "One recent study could not replicate the TGFβ1 (−509) SNP association with fibrosis in a retrospective analysis of breast cancer patients." (PMID 17325707, 2007). "As these results are not our original hypotheses, our observation that TGFB1 polymorphisms are inversely associated with ER+ breast cancers should be considered hypothesis generating, and needs further replication." (PMID 17848193, 2007). "However, studies examining the association between TGFB1 polymorphisms and breast cancer risk have failed to yield a clear picture." (PMID 17848193, 2007). "However, data about the influence of TGFβ1 on breast cancer development are conflicting." (PMID 16404434, 2006). "Transforming growth factor beta-1 (TGF-beta 1) has been proposed as a mediator of tumour growth in a number of tumours and cell lines including prostate, and in a recent study was shown to be up-regulated in the stroma of breast cancer tissue following treatment with the anti-oestrogen tamoxifen." (PMID 8286194, 1994). "MCF-7 breast cancer cells yielded comparable results, with a significant increase in TNT observed in cells treated with TGFβ-1, IL-6, and HGF." (PMID 41750361, 2026). "In breast cancer, transdifferentiation of BMSCs into distinct CAF subsets is mediated by myeloid zinc finger 1 (MZF1)-induced TGFβ1 through the osteopontin–TGF-β1 pathway." (PMID 40805183, 2025). "In this study, we have highlighted the significance of TGFβ-1, IL19, CXCR4, BMP1, IL1A, VCAN, PDK1, and WNT2 in breast cancer pathology." (PMID 41348904, 2025). "Our findings in translational relevance open new avenues for using TGFβ-1 and CXCR4 as combinatorial therapeutic targets or prognostic markers, especially in the more aggressive subtypes of breast cancer." (PMID 41348904, 2025). "We compared the TGFβ-1, CXCR4, IL19, BMP1, VCAN, and WNT2 expression in different subtypes of breast cancer, and the results demonstrated that BMP1, and WNT2 were consistently overexpressed in HER-2 subtype." (PMID 41348904, 2025). "Published studies have shown that the roles of transforming growth factor isoforms TGFB1, TGFB2, and TGFB3 in breast cancer prognosis are context-dependent." (PMID 41373732, 2025). "It was previously shown that MMP-2 and MMP-9 activity is increased by TGFβ1 treatment in a time- and dose-dependent manner in HCC1806 breast cancer cells." (PMID 40535569, 2025). "Given the role of TGFβ-1 and CXCR4 in the breast cancer pathology especially their dysregulation in the said cancer, it is very important to develop better treatment interventions to address the same." (PMID 41348904, 2025). "It has been reported that phenolics secoiridoids such as HTyr, Ole aglycone in EO, act as anti-aging phytochemicals by inhibiting TGFB1-induced fibrogenic and oncogenic EMT in Madin–Darby canine kidney (MDCK) cells and human breast cancer (MCF-7) cells." (PMID 40233022, 2025). "TGFB1, ERBB2, and CD68 form a signaling network that impacts cancer progression, invasion, and resistance to therapy in HER2-overexpressing breast cancer tumors." (PMID 41373732, 2025). "Conversely, in breast cancer, mast cells recruited and activated by tumor cells can induce transcriptional changes in genes such as SPP1, PDCD1, IL17A, TGFB1, KITLG, and IFNG, leading to anti-tumor effects." (PMID 40495762, 2025). "By employing UALCAN, we examined the pattern of expression for TGFβ-1, IL19, CXCR4, BMP1, VCAN, and WNT2 in breast cancer." (PMID 41348904, 2025).
breast cancer (continued). "Breast cancer tumorspheres presented a statistically significant increase in CXCL8, IL6, IL6R, and NFKB1 mRNA levels in comparison to adherent cell culture, while TGFB1 mRNA expression was decreased." (PMID 39336151, 2024). "TGFβ1 derived from osteoblasts stimulates the AKT/NFκB axis, thereby enhancing the migration of breast cancer cells mediated by transmembrane adhesive receptors integrin β1 and β3." (PMID 38041134, 2023). "Of note, both TGFB1 and STAT6 are well-known for their immune evasive roles in breast tumor microenvironment while STAT1 is proposed as a potential biomarker in breast cancer patients undergoing immune checkpoint therapy." (PMID 36809986, 2023). "For the negatively correlated gene cluster, TGFBR2 as well as TGFB1 showed a significant correlation in the same direction in the METABRIC data set, further establishing suppression of TGFß signaling by GRHL2 in breast cancer cells." (PMID 36691073, 2023). "In this study, we combined cellular models of TGFβ1-induced EMT with RNA sequencing analysis, database screening and invasion assays to identify chemotactic mechanisms linking TGFβ1 to EMT and lymphatic dissemination of breast cancer cells." (PMID 38055067, 2023). "From 144 intersection targets of Ecliptae Herba and breast cancer, we then obtained the hub targets EGFR and TGFB1 of Ecliptae Herba for breast cancer treatment by constructing PPI network and MCODE function." (PMID 37832105, 2023). "Together, the results indicate that TGFβ1, in addition to its capacity to induce EMT in breast cancer cells, can act on lymphatic endothelial cells to promote the expression of factors, which are chemotactic for breast cancer cells with mesenchymal properties." (PMID 38055067, 2023). "Overexpression of the cytokine TGFβ1, a potent inducer of EMT, in breast cancer tissues and plasma samples from breast cancer patients is associated with lymph node metastasis." (PMID 38055067, 2023). "Recent research has shown that RAB31 is capable of inhibiting the TGF-β pathway by decreasing TGFB1 mRNA and antigen levels, thereby exerting an impact on the migration, invasion, and apoptosis of breast cancer cells." (PMID 37207166, 2023). "Based on this, we set out to explore possible additional chemotactic mechanisms linking TGFβ1 to EMT and lymphatic dissemination of breast cancer cells." (PMID 38055067, 2023). "A recent study reported that the TGFβ1 signalling pathway upregulates the expression of PTHLH in lung and breast cancers." (PMID 35406121, 2022). "A further four more proteins, namely, TGFβ1, DAG1, LGALSBP3, and LOXL2, were found to be common between DCIS and breast cancer (all grades)." (PMID 36010848, 2022). "For example, monoclonal antibodies or bispecific antibodies corresponding to antigens such as EGFR, VEGFR, PD-L1, TGFB1, and CTLA-4 have been used to treat tumors, such as acute lymphoma leukemia, colorectal cancer, and breast cancer." (PMID 36523779, 2022). "It has been reported that HER2 and the TGFβ1-SMAD pathway are correlated and that there are synergistic effects of TGFβ and HER2 in the progression of breast cancer." (PMID 35650563, 2022). "Although the combination of Tranilast and tamoxifen has also decreased the expression levels of TGFβ1, TGF-β2, TGF-β3 TGFβ-RI, and TGFβ-RII, it increased the level of TGFβ-RIII in breast cancer cells (MCF-7)." (PMID 34452560, 2021). "Increased MDSCs in TME up-regulated transforming growth factor-beta 1 (TGF-β1), vascular endothelial growth factor (VEGF), and Interleukin-10 (IL-10) in rodent breast cancer models." (PMID 34869378, 2021). "The mRNA levels of EPAS1 as well as TGFB1, VEGFA and CA9, were confirmed to be positively correlated with those of SIPA1 in these two pairs of breast cancer cells and BT549, another TNBC cell line." (PMID 35096814, 2021).
breast cancer (continued). "TGFβ1 knockdown reduced the migration and invasiveness of BATF-overexpressing breast cancer cells, whereas incubation with TGFβ1 enhanced the migration and invasiveness of calycosin-treated breast cancer cells." (PMID 34096887, 2021). "Conversely, TGFβ1 treatment decreased E-cadherin levels and increased N-cadherin, Vimentin, CD147, MMP2 and MMP9 expression levels in the breast cancer cells." (PMID 34096887, 2021). "More precisely, osteoblast-derived TGFβ1 stimulates, among others, the AKT/NFKB axis and, therefore, enhances the transmembrane adhesion receptor integrin β1 and β3-mediated migration of breast cancer cells." (PMID 34064589, 2021). "Earlier, we demonstrated that the RAC1 splice isoform, RAC1b, can protect cells from mesenchymal transition by TGFβ1 and an increase in TGFβ1 and RAC1-driven cell motility in both PDAC and breast cancer cells." (PMID 34771704, 2021). "In fact, high plasma levels of TGFβ1 correlate with reduced overall survival in CRC and breast cancer patients." (PMID 34789823, 2021). "Through database analysis, we found that the expression levels of TGFB1 and TGFBR1 in breast cancer are correlated with the infiltration levels of multiple immune cells." (PMID 34485309, 2021). "Through analysis of the TIMER database, we found that the expression of TGFB1, TGFBR1, and TGFBR2 are correlated with the infiltration levels of various immune cells in breast cancer." (PMID 34485309, 2021). "Studies in breast cancer models of lung metastasis have identified that cancer cells with high AXL expression also highly express thrombospondin-2 and this drives TGFβ1-dependent lung colonization." (PMID 33014869, 2020). "Metformin modulates the following axes: miR-miR-708/CD47 in breast cancer, miR-27b/ENPP1 in breast cancer, 26a/EZH2 in pancreatic cancer, and blocks TGFβ1-induced upregulation of miR-181a and downregulation of miR-96 in breast cancer." (PMID 32512882, 2020). "We thus examined the relationship between the mRNA expression levels of TGFB1 (TGFβ), CTNNB1 (β-catenin), SNAI1, SNAI2 and ZEB1 and those of Sipa1 in TCGA breast cancer patient samples." (PMID 32193333, 2020). "Several growth factor–related breast cancer genes (EGF, IGF1, IGF1R, IGF2, IGFBP3, IL10, TGFB1, and VEGF), including 26 SNPs, were used as simulation data to evaluate existing algorithms and the proposed HTGA." (PMID 32554381, 2020). "In various epithelial cell types, that is, a normal ovarian epithelial cell line, the MDA-MB-231 breast cancer and a TGFβ receptor-expressing LS174T colon cancer cell line, TGFβ pathway activity increased after stimulation with TGFβ1." (PMID 30733525, 2019). "TGFβ1-mediated inhibition of miR-196a-3p and consequent activation of NRP2 promotes a metastatic phenotype of breast cancer cells." (PMID 30717262, 2019). "Cdk5 is essential for TGFβ1-induced EMT and breast cancer progression, further linking Cdk5 to aggressiveness and EMT." (PMID 30452490, 2018). "Our results suggest that ADAMTS9 is a TSG epigenetically inactivated in breast cancer, which functions through blocking EGFR‐ and TGFβ1/TβR(I/II)‐activated AKT signaling." (PMID 29193730, 2018). "In mammary tumor explants expressing activated Neu/ErbB-2 receptor, the Rac1/Cdc42-GAP, CdGAP, was required for TGFβ1 to induce migration and invasion." (PMID 29415466, 2018). "Higher C‐ets‐1 and lower miR‐128‐3p expression levels intensify MET signaling and thereby suggest TGFβ1 as a regulator of HGF‐mediated migration in MCF10A and breast cancer cells." (PMID 30004628, 2018). "It has been shown that TGFβ1 directly acts on the basal‐like breast tumor cell line MDA‐MB‐231 and that this drives metastatic processes of breast cancer cells by its binding to TGFBR2." (PMID 30004628, 2018). "We propose that this occurs in an autocrine manner, where leptin induces TGFB1 expression and secretion, which then acts on TGFBRI and TGFBRII receptors of breast cancer cells." (PMID 28542577, 2017).
breast cancer (continued). "All of which laid the foundation for the specific molecular mechanism of TGFβ1-miRNA-NRP2 this axis for promoting breast cancer metastasis, and provide an important molecular target for breast cancer treatment." (PMID 28418877, 2017). "Although the role of TGFβ isoforms in tumors remains debatable, most studies that focus on exosomal TGFβ report that TGFβ1 enhances EMT in diverse cancer models, and TGFβ2 in milk exosomes drives breast cancer cells towards EMT." (PMID 29221185, 2017). "Researches have shown that ZEB2, TGFB1, MDM2 are important downstream effectors that can be inhibited by GATA3 in breast cancer." (PMID 28599307, 2017). "We have also identified binding of TGFB1 to its receptor as a new pathway contributing to the leptin-induced EMT and CSC effects on breast cancer cells." (PMID 28542577, 2017). "Cysteine cathepsin functions during TGFβ-1 induced EMT were analyzed using NMuMG (normal murine mammary gland) cells and a novel MMTV-PyMT breast cancer cell line “iPL32” (immortalized Polyoma Luciferase transgenic), respectively." (PMID 25744631, 2015). "Our results show an important role of lysosomes and lysosomal proteolysis in cellular remodeling during TGFβ-1 induced EMT and the acquisition of an invasive phenotype of breast cancer cells." (PMID 25744631, 2015). "Mir-106 too was described as deeply involved in TGFβ protumorigenic signaling through targeting of SMAD7, in turn inducing EMT in breast cancer, similarly to miR-10b, induced by TGFβ1 and promoting EMT in breast cancer." (PMID 26188123, 2015). "Increasing evidence suggests that transforming growth factor-beta 1 (TGF-β1) triggers epithelial to mesenchymal transition (EMT) and facilitates breast cancer stem cell differentiation." (PMID 26482896, 2015). "In particular, IFNγ, leptin, TGFβ1, TIMP1, TIMP2, thrombopoietin and VEGF levels were significantly inhibited by anandamide in the conditioned medium of MDA-MB-231 breast cancer cells." (PMID 25147760, 2014). "Here we report on our findings for biomarkers previously related to breast cancer, epidermal growth factor (EGF), transforming growth factor-beta 1 (TGF-β1), and adiponectin." (PMID 24252368, 2013). "KLK6 is thought to act on the TGFβ1 signal transduction pathway and thereby influence cell migration and motility, and KLK6 alters the expression of TGFβ1 in breast cancer cells." (PMID 22436421, 2012). "While some studies failed to reveal any change in plasma TGFβ value in patients with breast cancer, other reports demonstrate that patients with more advanced tumours have higher serum levels of TGFβ1, suggesting that serum TGFβ1 may reflect the severity of invasive breast cancer." (PMID 16404434, 2006). "Clinically, plasma Tgfβ1 levels correlated positively with the MO-MDSC/PMN-MDSC ratio across multiple cancer types including CRC, ovarian cancer, and breast cancer, suggesting its potential as a biomarker for stratifying the MO-MDSC/PMN-MDSC ratio in cancer patients." (PMID 41360769, 2025). "In neuroblastoma and mesothelioma, ERK5 is activated by PI3K/AKT signaling; in breast cancer, STAT3 enhances MEK5 expression; and in renal epithelial cells, TGFβ1-induced MEK5/ERK5 activation occurs through ALK and p38 MAPK, facilitating MEF2C-mediated transcription." (PMID 40672381, 2025). "The expression pattern of TGFβ-1, IL19, CXCR4, BMP1, VCAN, and WNT2 in different molecular subclasses of Breast Cancer revealed that TGFβ-1, IL19, CXCR4, BMP1, VCAN, and WNT2 mRNA levels are higher in luminal A followed by luminal B, HER2 and Basal like respectively." (PMID 41348904, 2025). "TGFβ-1, VCAN, and IL19 are comparatively expressed more in Luminal subtype of breast cancer." (PMID 41348904, 2025).